IL6 (interleukin 6)
Diseases named in the same sentence as IL6 in open-access papers (continued):
Sharing a sentence is not in itself a finding about the gene and the disease.
periodontitis (continued). "Immune-inflammatory agents, namely CRP, TNF-α, CXCL10, IL-6, IL-18, sVCAM-1, sICAM-1, IP-10 and MCP-1, have been found in high concentrations in the circulating blood of pregnant individuals diagnosed with preeclampsia who also have periodontitis." (PMID 41394354, 2025). "Furthermore, ELISA analysis of periodontitis-related markers in the blood showed that W. cibaria CMU exhibited significant preventive ability to induce periodontitis in TNF-α, IL-6, MMP-1, and MMP-9 categories." (PMID 40007939, 2025). "Therefore, IL-6 and TGF-β1 were selected due to their direct involvement in the specific pathways such as IL6/JAK/STAT3 and TGF-β1/SMAD linking periodontitis and renal pathology." (PMID 40452929, 2025). "In patients with periodontitis and hyperlipidemia, intensive periodontal treatment reduced the serum triglyceride and proinflammatory cytokine levels, that is, tumor necrosis factor-alpha (TNF-α), interleukin (IL)-1β (IL-1β), and IL-6." (PMID 40552326, 2025). "Systemically, chronic low-grade inflammation from periodontitis elevates circulating RANKL and proinflammatory cytokines (IL-1β, IL-6, and TNF-α), which may exacerbate skeletal resorption in osteoporosis-prone individuals." (PMID 41466921, 2025). "A recent systematic review on diagnostic sensitivity and specificity of host‐derived biomarkers, assessing only saliva as a sampling source, concluded that certain salivary biomarkers (IL‐6, MMP‐8, IL1‐beta) can potentially be useful alone or in combination, for the diagnosis of periodontitis." (PMID 39801446, 2025). "In the periodontitis model, PU.1-mediated CTSS regulation in macrophages correlates with inflammatory pathway activation (e.g., p38 and NF-κB signaling) and elevated levels of inflammatory factors (e.g., IL-6)." (PMID 40692794, 2025). "Periodontitis is characterized by a persistent immune inflammatory response to bacterial biofilms, leading to systemic dissemination of cytokines such as tumor necrosis factor (TNF)-α, IL-1β, IL-6, and prostaglandins." (PMID 40941475, 2025). "Individuals with periodontitis exhibit increased serum levels of inflammatory markers, such as C-reactive protein (CRP) and interleukin-6 (IL-6), suggesting that EtO may exacerbate inflammation." (PMID 40430168, 2025). "This synergistic interplay among IL-6, IL-1β, and TNF-α drives extracellular matrix degradation, osteoclastogenesis, and progressive alveolar bone resorption, thereby contributing to the irreversible tissue breakdown characteristic of advanced periodontitis." (PMID 41007333, 2025). "However, IL-17, IL-6, and IL-4 in stage III Grade A and stage IV Grade B periodontitis remained elevated." (PMID 40002786, 2025). "In this review, the regulatory role of exosomal miR-223-3p in periodontitis was also highlighted, specifically its ability to suppress NLRP3 inflammasome-mediated pyroptosis and the release of pro-inflammatory cytokines such as IL-1β and IL-6 in macrophages." (PMID 41322905, 2025). "Similarly, reported that in saliva, the dual combinations of IL‐1β, IL‐6 and MMP‐8 have an excellent ability to detect periodontitis and a good capacity to detect non‐periodontitis, but a meta‐analysis of gingival crevicular fluid biomarkers was not possible." (PMID 39801446, 2025). "Conversely, IFN-γ, IL-4, IL-6, IL-10, and IL-12p70 exhibited no statistically significant changes across healthy, gingivitis, and periodontitis sites." (PMID 41303313, 2025). "Periodontitis affects endothelial function through systemic inflammation involving mediators such as CRP, IL-6, and TNF-α that can affect endothelial function, which may contribute to hypertension development." (PMID 40735233, 2025). "This suggests that CO could mitigate the destructive effects of IL-6 and TNF-α, providing a novel approach to controlling inflammation in periodontitis." (PMID 40085302, 2025).
periodontitis (continued). "A different pattern was observed for IL-6 (F = 0.1871 and p = 0.05): while levels were lower in T1DM individuals with healthy or gingivitis status, a significant increase was noted in those with periodontitis (p = 0.02)." (PMID 41280935, 2025). "This study aimed to evaluate the effectiveness of RSV mouthwash as an adjunct to NSP treatment of periodontitis in comparison to a positive control (chlorhexidine [CHX]) and a negative control (placebo) and to evaluate the change in the salivary level of IL-6 and RANKL." (PMID 39251207, 2025). "Additionally, levels of certain inflammatory markers, such as PCR, IL-6, and MMP-9, were significantly higher in serum in patients with EA and chronic periodontitis, suggesting a systemic inflammatory state." (PMID 40231144, 2025). "Conversely, experimental data indicate that periodontitis may aggravate UC by inducing intestinal dysbiosis and promoting pro-inflammatory cytokine secretion, including TNF-α and IL-6 in mice." (PMID 41007498, 2025). "As a key pro‐inflammatory cytokine involved in both RA and PD, IL‐6, alongside CRP, a marker of systemic inflammation, suggests that periodontitis microbiota induced a more intense systemic inflammatory response, mirroring clinical findings in patients with RA and concomitant PD." (PMID 41321261, 2025). "Hence, our objective is to explore the outcomes of NSPT in modulating periodontal parameters, renal function parameters, and concentration of inflammatory biomarkers (IL-6 and TGF-β1) in patients diagnosed both with CKD and periodontitis." (PMID 40452929, 2025). "IL-6 levels were again elevated in diabetic patients (F = 15.24, p = 0.0001), consistent with GCF findings, with significant differences observed in the periodontitis group (p = 0.0009)." (PMID 41280935, 2025). "We hypothesise that NSPT improves periodontal parameters, enhances renal function, and reduces the concentrations of IL-6 and TGF-β1 in CKD patients with periodontitis." (PMID 40452929, 2025). "The link between periodontitis and atherosclerotic coronary artery disease seems to stem from both the persistent microbial load and the inflammatory response, as evidenced by elevated levels of systemic inflammatory markers like CRP and IL-6." (PMID 40217896, 2025). "System inflammation due to periodontitis results in elevated TNF-α, CRP AND IL-6 in women with GDM." (PMID 41394354, 2025). "Elevated levels of pro-inflammatory cytokines, such as IL-1β and IL-6, along with matrix metalloproteinases like MMP-8, contribute to the degradation of connective tissue and bone resorption, driving the clinical manifestations of periodontitis." (PMID 40283677, 2025). "Periodontitis has been shown to contribute to the development and progression of NAFLD through the mediation of inflammatory cytokines, including interleukin (IL)-1β, IL-6, and TNFα." (PMID 40142822, 2025). "Another common mechanism between periodontitis and CRC is IL-6 trans-signaling." (PMID 40944094, 2025). "Similar levels of IL-6 and IL-8 in smokers and non-smokers indicate that smoking has no major impact on systemic serum concentrations in severe periodontitis patients." (PMID 38627806, 2024). "However, our results suggest that osteoclastogenesis in periodontitis is mainly dependent on RANKL and IL-6, as the expression of Tnfsf11 and Il6 was markedly increased, whereas the change in Tnf expression was mild." (PMID 38548743, 2024). "This study affirmed that quercetin possessed the ability to restore osteo-/angiogenic differentiation capacity as well as inhibit the pro-inflammatory factors’ production including IL-6 and TNF- α in inflammatory PDLSCs, which was beneficial for alveolar bone regeneration in periodontitis." (PMID 38449005, 2024). "The results of the real-time PCR showed that the expression levels of all targeted molecules (ACE2, IL-6, miR-200c-3p, and miR-421-5p) were detected in the saliva of all participants with and without periodontitis." (PMID 39917640, 2024).
periodontitis (continued). "The meta-analysis revealed significant reductions in markers such as high-sensitivity C-reactive protein (his-CRP), interleukin (IL)-6, and plasma glucose, along with improvements in Flow-Mediated Dilation (FMD) and diastolic blood pressure after periodontitis treatment." (PMID 39607148, 2024). "Periodontitis induces a chronic inflammatory response in the periodontal tissues, characterized by the release of pro-inflammatory cytokines such as interleukin-1 beta (IL-1β), TNF-α, and IL-6." (PMID 39189252, 2024). "Compared to heathy subjects, elevated IL-6 levels exist in the saliva of patients with periodontitis, although these levels do not correlate with periodontitis progression." (PMID 38779873, 2024). "As periodontitis is both a local and a systemic condition, we determined the effect of Pg-inoculation on the induction of systemic inflammation by assessing the levels of proinflammatory cytokines such as IL-1β, TNF-α, IL-6, GM-CSF, VEGF, IL-17, and KC." (PMID 38892314, 2024). "Physical training resulted in a reduced levels of IL-1β, IL-6, TNF-α C-reactive protein and LPO and an increase in the levels of IL-10 in rats with periodontitis (p<0.05); a reduction in the inflammatory infiltrate and decreased fiber degradation was identified in histological analysis." (PMID 38843156, 2024). "In conclusion, the upregulation of IL-6, IL-17, and IL-35 in individuals with S III and S IV periodontitis, along with the observed correlation between IL-17 levels and PD, GI, and CAL, suggests a potential association between severe periodontitis and these cytokines." (PMID 39215253, 2024). "We also did not demonstrate statistically significant differences in IL-6 expression in the gingival tissue of patients with periodontitis and controls, as well as correlations of IL-6 with clinical parameters in patients with periodontitis." (PMID 39458264, 2024). "Comparing groups with or without periodontitis, they found an association between atherosclerosis and periodontitis to be associated with inflammatory CRP and IL-6." (PMID 38774039, 2024). "The presence of LPS during periodontitis induces the production of pro-osteoclastogenetic cytokines such as TNF-α, IL-1, IL-6 by osteoblasts and periodontal ligament fibroblasts, T cells, and B cells, leading to the production RANKL, which has a pivotal function in osteoclast differentiation." (PMID 39456522, 2024). "Interleukin-6 (IL-6) plays a pivotal role in periodontal disease, not only because it is intricately involved in the bone resorption process characteristic of periodontitis but also as a regulator of acute phase proteins in inflammation." (PMID 39917715, 2024). "In this study, the peripheral blood concentration of IL-6 was significantly higher in cancer patients than in non-cancer patients, and it was even higher in cancer patients with periodontitis compared to those without." (PMID 39015494, 2024). "The increased salivary levels of macrophage inflammatory protein (MIP)-1α and prostaglandin E2 (PGE2) but not interleukin (IL)-1β, IL-6, and IL-8 are reported in gingivitis, an initial stage of periodontitis." (PMID 38068492, 2023). "For example, Prevotella predominates in periodontitis and could exacerbate inflammatory disease by stimulating the production of inflammatory mediators such as CCL20, IL-8 and IL-6." (PMID 37808891, 2023). "In line with previous studies, the results of the present study showed that the EP group had significantly higher serum levels of IL-6, CRP, MMP-8, and ALP and lower levels of IL-10 than the control group confirming that the experimental model used was able to induce experimental periodontitis." (PMID 38033572, 2023). "Indeed, higher levels of pro-inflammatory cytokines (IL-1β, IL-6, TNF) were found in blood and gingival fluid in obese subjects with periodontitis compared to normo-weighted subjects with periodontitis." (PMID 37894804, 2023).
periodontitis (continued). "Additionally, higher levels of IL-6, IL-17A and IL-33 were detected in the saliva of SLE patients with chronic periodontitis." (PMID 36949458, 2023). "IL-6 and CRP levels on the severity of periodontitis in CAD in Indonesia were also evaluated." (PMID 37239434, 2023). "In addition, it has also been reported that IL-6 in serum induces neuroinflammation in the hippocampus and destruction of the BBB in a mouse model with experimental periodontitis." (PMID 37635786, 2023). "IL-6 and TNF-α are common inflammatory cytokines that are elevated in patients with periodontitis." (PMID 37645411, 2023). "Although the IL-6 and CRP levels were not significantly different between the two groups, IL-6 levels affected CRP levels in periodontitis patients with CAD." (PMID 37239434, 2023). "The increasing level of resistin in obese patients and rats with periodontitis might be due to its ability to recruit TNF-α and IL-6." (PMID 38069063, 2023). "We previously reported that sIL-6R was detected at higher levels in the GCF of periodontitis sites than in healthy sites and that these molecules induce MMP-1 expression in the secondary response to IL-6 produced by IL-1β and indirectly activate intracellular signaling pathways in HGFs." (PMID 36834667, 2023). "While in the established periodontitis mouse model, NAC‐S2 administration significantly decreases CEJ to ABC distance and suppresses the expression levels of pro‐inflammatory cytokines including TNF, IL‐6, and IL‐1β." (PMID 37647428, 2023). "In addition, patients with severe periodontitis have been shown to have higher CRP and IL-6 levels, which have been shown to decrease after periodontal therapy." (PMID 38132485, 2023). "IL-6 -572 C/G, CRP -757 A/G, and CRP -717 T/C gene polymorphisms; IL-6 levels; and CRP levels had no apparent effects on the severity of chronic periodontitis in CAD based on the path analysis." (PMID 37239434, 2023). "They observed an upregulation of mRNA levels for C-reactive protein (CRP) and interleukin 6 (IL-6) in adipose tissue in obese but not lean mice with periodontitis." (PMID 37237407, 2023). "Recent random effects meta-analyses demonstrated intermediate quality evidence that individuals with periodontitis had greater serum IL-6 levels than those without periodontitis among transplanted patients." (PMID 36769328, 2023). "IL-6 and IL-8 were significantly upregulated, and IL-10 was downregulated in the periodontitis group compared to the non-periodontitis group." (PMID 39697803, 2023). "Various inflammatory mediators, such as IL-6, IL-17A and MMP-8, are essentially involved in the pathogenesis of both PCOS and periodontitis, and especially, the expression and release of MMP-8 increase significantly during the aggravation of periodontal inflammation and the resultant destruction." (PMID 37794378, 2023). "IL-6, nitric oxide, IL-1B, TNF-α and osteoprotegerin are among the most present biomarkers in patients with periodontitis, and may be used in the future as a monitoring of periodontal disease." (PMID 37026605, 2023). "In the progression of periodontitis in human, NF-κB can be activated by LPS-induced Toll-like receptor 4 (TLR4) activation, which activates gene expression of multiple proinflammatory cytokines, such as IL-1, IL-6, and TNF-α." (PMID 36846719, 2023). "Moreover, some promising biomarkers of periodontitis were suggested, such as matrix metalloproteinase-8 (MMP-8), matrix metalloproteinase-9 (MMP-9), interleukin 1 beta (IL1β), and interleukin 6 (IL6)." (PMID 37535199, 2023). "A dysbiotic microbiome induced IL-6 and IL-23-dependent increase of TH17 cells in periodontitis." (PMID 36769328, 2023). "Regarding the absence of variation in IL-6 plasma levels throughout the induction and treatment of experimental periodontitis, our results are in contradiction with other data in the literature." (PMID 36840029, 2023).
periodontitis (continued). "Elevated levels of IL‐1β, IL‐6, and TNF‐α have been detected in inflamed gingival tissues of patients with periodontitis, which contributes to tissue destruction and the progress of periodontitis." (PMID 37506160, 2023). "One of the primary virulence factors of periodontitis, Pg-LPS, targets TLR4, which activates the NF-kB signaling pathway and triggers the secretion of inflammatory cytokines such as TNFα, IL-6, and chemokines, recruiting monocytes/macrophages to the site of infection." (PMID 38249288, 2023). "It was also proven, that the effective nonsurgical treatment of periodontitis leads to decrease of IL-6 on GCF." (PMID 37608339, 2023). "EXO-NET EVs display increased IL-6, IL-8, and IL-1β in periodontitis individuals compared to those without, with significantly reduced IL-10 expression." (PMID 39697803, 2023). "IL-6 is the dominant proinflammatory mediator in chronic periodontitis, affecting various functions of both specific and nonspecific immune cells." (PMID 37895087, 2023). "Our previous studies have shown that the concentration of the soluble form of the IL-6 receptor (sIL-6R), an IL-6 agonist released by lymphocytes and macrophages, in the gingival crevicular fluid (GCF) was significantly higher in periodontitis sites than in healthy sites." (PMID 36834667, 2023). "Additionally, IL-6 significantly increases the production of VEGF, bFGF, and cathepsin B in human gingival fibroblasts and synergistically induces angiogenesis in periodontitis lesions." (PMID 36275775, 2022). "Another explanation may be that telomere dysfunction can activate the production and secretion of inflammatory factors such as IL-6 and TNF-α, leading to the development of periodontitis." (PMID 36601105, 2022). "Significant higher salivary levels of IL-6 and IL-1β were found in the periodontitis group when compared to the nonperiodontitis group (p=0.005; p < 0.001, respectively)." (PMID 35368315, 2022). "Notably, circulating inflammatory mediators such as TNF-α, IL-6 and CPR serve as the link between systemic chronic inflammatory diseases and chronic periodontitis, and better early diagnosis of periodontitis by these inflammatory biomarkers." (PMID 36570162, 2022). "Plumbagin inhibits chronic periodontitis by downregulating the TNF-α, IL-1β, and IL-6 expressions." (PMID 36589679, 2022). "Other biomarkers such as HbA1c, and IL-6 showed higher levels in non-treated periodontitis when compared to treated subjects, but these differences were not significant." (PMID 35906340, 2022). "IL-6 and TNF-α level were regulated by miR-21 in macrophages of periodontitis." (PMID 35931990, 2022). "In our study, SERPINA1 was the core gene in PPI and correlated with seven ERS-related genes including ERLEC1, VWF, EDEM2, DERL3, APOE, IL6, and CXCL8, suggesting that SERPINA1 may play an essential role in the pathological process of periodontitis." (PMID 36072904, 2022). "The present results revealed that IL-6 concentrations were increased in PB, but not in the cancer/periodontitis microenvironment." (PMID 35804048, 2022). "Compared with non-NSPT, NSPT reduced the serum level of IL-6 in CAD patients with periodontitis, but the difference was not statistically significant." (PMID 36243997, 2022). "Elevated IL-6 and CXCL2 gingival levels were also found in human periodontitis." (PMID 34024010, 2022). "Enhanced IL-6 and CXCL2 levels have also been detected in the gingiva in human periodontitis." (PMID 35478496, 2022). "In contrast to periodontitis, orthodontic tooth movement did not increase the IL-6 and CXCL2 expressions in rat gingiva." (PMID 34024010, 2022). "The presence or absence of periodontitis was assessed and the peripheral blood (PB) concentrations of IL-6, immunosuppressive cytokines (VEGF, TGF-β1, and CCL22) and proportion of T regulatory cells (Treg, CD3 + CD4 + CD25 + Foxp3 +) were measured." (PMID 35804048, 2022).